NYAP2 (neuronal tyrosine-phosphorylated phosphoinositide-3-kinase adaptor 2)
Description:
Activates PI3K and concomitantly recruits the WAVE1 complex to the close vicinity of PI3K and regulates neuronal morphogenesis.
Synonyms: KIAA1486
Tractability: PROTAC: ubiquitination databases record sites on it.
Gene: Protein-coding gene on chromosome 2 (225,399,710 to 225,729,887, forward strand). Ensembl gene ENSG00000144460.
Subcellular location (Human Protein Atlas): Cytosol; Microtubules; Primary cilium; Basal body; Cytokinetic bridge; Mitotic spindle; Nucleoplasm
Gene Ontology:
Molecular function: protein binding
Biological process: neuron projection morphogenesis; phosphatidylinositol 3-kinase/protein kinase B signal transduction
Genetic constraint (gnomAD): Loss-of-function variants: 21 observed, 43.4 expected, observed/expected ratio (o/e) 0.48, 90% interval 0.34 to 0.7. The upper end of that interval is the gene's LOEUF score, 0.7, which puts it in group 2 of 6, group 1 being the genes least tolerant of losing a copy. Missense variants: 825 observed, 793.26 expected, observed/expected ratio (o/e) 1.04, 90% interval 0.98 to 1.1. Synonymous variants: 370 observed, 350.11 expected, observed/expected ratio (o/e) 1.06, 90% interval 0.97 to 1.15.
Homologues: Orthologues: chimpanzee NYAP2 (99% identical), macaque NYAP2 (99% identical), rabbit NYAP2 (95% identical), pig NYAP2 (94% identical), mouse Nyap2 (92% identical), rat Nyap2 (92% identical), dog NYAP2 (92% identical), guinea pig NYAP2 (82% identical), tropical clawed frog nyap2 (76% identical), zebrafish nyap2a (57% identical), zebrafish nyap2b (48% identical). Paralogues in human: NYAP1 (33% identical).
Diseases named in the same sentence as NYAP2 in open-access papers:
NYAP2 is named in the same sentence as 8 diseases in open-access papers, as found by Europe PMC text mining. Sharing a sentence is not in itself a finding about the gene and the disease. The quoted sentences say what the papers report.
gastric cancer (1 paper, 2021). A primary or metastatic malignant neoplasm involving the stomach. "Consistently, this study found that the rs140991639 loci in NYAP2 were associated with BH2, which may be related to the occurrence of gastric cancer." (PMID 34565479, 2021).
tumor (1 paper, 2020). "Some of these genes may be involved in the proliferation and invasion of tumor cells; for example, NYAP2 is reported to activate PI3K, Akt and Rac1, and mediates remodeling of the actin cytoskeleton, whereas ZNF277 regulates cell migration and invasion through phosphatase and tensin homolog (PTEN)." (PMID 32986753, 2020).
NYAP2 also shares sentences with these, for which no sentence is quoted: atherosclerosis (1 paper); cancer (1); cognitive decline (1); ischemic stroke (1); sarcopenia (1); type 2 diabetes (1).